NEB (nebulin)
Diseases named in the same sentence as NEB in open-access papers (continued):
Sharing a sentence is not in itself a finding about the gene and the disease.
myopathy (32 papers, 2008 to 2025). A disease of the muscle in which the muscle fibers do not function properly. "This ∼100 kb in‐frame deletion encompasses NEB exons 14–89, causing distal nemaline/cap myopathy in a three‐generation family." (PMID 40525497, 2025). "Patient 11 also carried an additional deletion in NEB, a gene associated with myopathies following an autosomal recessive pattern of inheritance." (PMID 37035729, 2023). "So far only Fbxo9, being upregulated in a hindlimb unloading model and the association of Fbxo30 in Nebulin-mediated myopathy are known." (PMID 36969608, 2023). "Patients from families 1 and 2 died from a severe myopathy shortly after birth, and both were found to harbour NEB mutations." (PMID 23826317, 2013). "NEB mutations typically cause inherited myopathies, but interestingly, cilia-related pathology could be associated with missense NEB variants because the process by which cilia form is dependent on the actin cytoskeleton." (PMID 36920900, 2023). "Finally, the NEB gene encodes the protein Nebulin, and pathogenic variants in this gene cause mainly myopathy following an AR pattern of inheritance." (PMID 37035729, 2023). "Cores have also been observed in myopathy patients with nebulin mutations." (PMID 32483185, 2020). "The reduced levels of tissue nebulin are commonly associated with myopathy." (PMID 22949810, 2012). "Besides unravelling the biology of nebulin, these studies are particularly helpful in understanding the patho-mechanism of myopathies caused by NEB mutations, providing knowledge which constitutes the critical first step towards the development of therapeutic interventions." (PMID 31982973, 2020). "Large dominant NEB deletions have previously been reported in two separate families (F24 and F25) with distal nebulin myopathy." (PMID 40517164, 2025). "Five synonymous NEB, RYR1, and TTN variants were found to impact on splicing in three families with NM, one family with core myopathy and one family with CNM, respectively." (PMID 38982518, 2024). "Indeed, 5 out of the top 10 transcripts with the most AS events corresponded to sarcomeric genes, including TTN and NEB, indicating that abnormal nuclear pre-mRNA splicing of functionally important sarcomeric genes could contribute to the pathogenic mechanism of the myopathy in our family." (PMID 37000196, 2023). "Case 7 and 11 in our study showed distal muscle weakness with NEB gene mutations, which is in accordance with the study by Kiiski, who reported distal nemaline/cap myopathy with a large deletion in the nebulin gene." (PMID 33742414, 2022). "The peptides in the super repeat region of nebulin are binding sites for kelch like family member 40 (KLHL40), loss of which causes a nemaline-like myopathy." (PMID 32660935, 2020). "The Compound-Het myopathy takes place while nebulin expression is normal, thin filament lengths are slightly increased and crossbridge kinetics are unaltered." (PMID 32483185, 2020). "In brief, the patient’s muscles produced a mix of full-length and truncated nebulin, resulting in a slowly progressive myopathy." (PMID 31992366, 2020). "The first report of a distal recessively inherited nebulin myopathy was provided by Wallgren-Pettersson et.al., who described seven Finnish patients from four different families, who carried two different missense mutations in NEB gene in homozygosity." (PMID 32456280, 2020). "P25 showed unusual late onset of symptoms for NEB mutations and biopsy showed features supporting a diagnosis of CAP myopathy." (PMID 26809617, 2016). "NEB codes for the contractile unit scaffold protein nebulin and mutations in NEB usually give rise to a mild childhood or adult onset myopathy, but also rare fatal cases as for our patients have been reported." (PMID 23826317, 2013). "The phenotypes of NEB and POLAMT variants are partial in accordance with myopathy." (PMID 37860673, 2023).
myopathy (continued). "Interestingly, all of these genes are associated with genetic (cardio)myopathies in humans (TTN, NEB, MYBPC1, TNNT3 and TPM1) or mice (PDLIM3)." (PMID 37000196, 2023). "First, we reported 18 novel variations in 6 myopathy-causing genes, including RYR1, NEB, ACTA1, DNM2, TTN and TNNT1, and we described the clinical discrepancy between our patients and previous reports, especially in RYR1- and TNNT1- related myopathy." (PMID 35081925, 2022). "Thus, it was suggested that this novel mutant nebulin protein has a dominant‐negative effect, explaining the first documented dominant inheritance of nebulin‐caused myopathy." (PMID 40525497, 2025). "Notably, mutations in NEB, NRAP, and FLNC have been associated with NM and other myopathies." (PMID 28826497, 2017). "Moreover, mutations in NEB was not a known cause of CAP myopathy at the time of clinical evaluation and had only been reported recently in a single case." (PMID 26809617, 2016). "Among the myopathies, emerging data suggest a specific role for LCD-containing RBPs such as TDP-43 and hnRNPA2/B1 in regenerating muscle, where they are thought to stabilize large muscle-specific transcripts (e.g., TTN, NEB), aid in their transport, and facilitate pre-mRNA splicing." (PMID 35484142, 2022).
cancer (8 papers, 2013 to 2025). A tumor composed of atypical neoplastic, often pleomorphic cells that invade other tissues. "NEB was also identified as a potential cancer-related gene, but research into NEB in CRC is still in its early stages." (PMID 35975176, 2022).
tumor (8 papers, 2018 to 2025). "Mutations in certain large genes, such as TTN, NEB, SYNE1, MUC16, and OBSCN, have previously been associated with tumor mutation burden (TMB)." (PMID 38473427, 2024).
neuromuscular disease (5 papers, 2014 to 2021). "Exome sequencing allows a rapid and parallel screening of most human genes, and is suitable and efficient for the diagnosis of neuromuscular diseases and the analysis of large genes such as NEB, frequently mutated in NM." (PMID 24725366, 2014). "For example, several neuromuscular disease-causing genes, such as NEBULIN (NEB) and SELENON (SEPN1), overlap these difficult to sequence regions." (PMID 32277129, 2020). "Within this cohort, mutations were found in eight previously known neuromuscular disease genes (CHRND, CHNRG, ECEL1, GBE1, MTM1, MYH3, NEB and RYR1) and four novel neuromuscular disease genes were identified and have been published as separate reports (GPR126, KLHL40, KLHL41 and SPEG)." (PMID 26578207, 2015). "Mutations were found in eight previously known neuromuscular disease genes (CHRND, CHNRG, ECEL1, GBE1, MTM1, MYH3, NEB and RYR1) and four novel neuromuscular disease genes (GPR126, KLHL40, KLHL41 and SPEG)." (PMID 26933539, 2015).
infection (3 papers, 2011 to 2024). The state of being infected such as from the introduction of a foreign agent such as serum, vaccine, antigenic substance or organism. "Genes encoding protein components of the cytoskeleton (NEB, MYOM2, MYOZ1, and MYBPC1) and surfactant proteins (A1, C, and D) were among the most significantly downregulated genes upon infection with swH1N1." (PMID 39247193, 2024). "Several genes, such as cadherin-like molecule 26 (CDH26), nebulin (NEB), deiodinase, iodothyronine, type II (DIO2), and solute carrier family 38, member 1 (SLC38A1), were significantly up-regulated during both the primary infection and reinfection." (PMID 21414188, 2011). "Interestingly, we have identified elevated serum levels of NEB, VTN, and TTN in SVM patients, while in non-severe infection, serum levels of these candidates were found to be nearly similar compared to the healthy controls." (PMID 27090372, 2016).
NEB also shares sentences with these, for which no sentence is quoted: congenital myasthenic syndrome (2 papers); gastric cancer (2); Nemaline myopathy-2 (2); ophthalmoplegia (2); achondroplasia (1); achromatopsia 2 (1); arthrogryposis (1); asphyxiating thoracic dystrophy 3 (1); cardiac hypertrophy (1); Central core disease (1); conduction disorders (1); congenital muscular dystrophy (1); diabetes mellitus (1); diabetic cardiomyopathy (1); Duane-radial ray syndrome (1); Duchenne muscular dystrophy (1); epilepsies (1); glaucoma (1); glioblastoma (1); Hydrocephalus (1); hydrops (1); melanoma (1); multiple pterygium syndrome (1); muscular disorders (1); myofibrillar myopathy (1); Myotonia (1); neuropathy (1); osteogenesis imperfecta type 1 (1); osteoporosis (1); ptosis (1).
A further 7 diseases each share a sentence with NEB in 1 paper.